SPATA1 (spermatogenesis associated 1)
Synonyms: SP-2; SPAP1
Gene: Protein-coding gene on chromosome 1 (84,506,300 to 84,567,379, forward strand). Ensembl gene ENSG00000122432.
Subcellular location: Cytoplasmic vesicle, secretory vesicle, acrosome
Subcellular location (Human Protein Atlas): Cytosol; Plasma membrane
Genetic constraint (gnomAD): Loss-of-function variants: 21 observed, 21.77 expected, observed/expected ratio (o/e) 0.96, 90% interval 0.68 to 1.39. The upper end of that interval is the gene's LOEUF score, 1.39, which puts it in group 5 of 6, group 1 being the genes least tolerant of losing a copy. Missense variants: 246 observed, 242.91 expected, observed/expected ratio (o/e) 1.01, 90% interval 0.91 to 1.13. Synonymous variants: 76 observed, 84.62 expected, observed/expected ratio (o/e) 0.9, 90% interval 0.75 to 1.09.
Homologues: Orthologues: chimpanzee SPATA1 (93% identical), macaque SPATA1 (91% identical), rabbit SPATA1 (78% identical), dog SPATA1 (76% identical), mouse Spata1 (71% identical), rat Spata1 (71% identical), pig SPATA1 (54% identical), tropical clawed frog spata1 (39% identical), zebrafish SPATA1 (30% identical).
Diseases named in the same sentence as SPATA1 in open-access papers:
SPATA1 is named in the same sentence as 3 diseases in open-access papers, as found by Europe PMC text mining. Sharing a sentence is not in itself a finding about the gene and the disease. The quoted sentences say what the papers report.
tumor (1 paper, 2023). "Moreover, many genes (PTN, SIAH2, FAM111B, TMEM43, FOSL2, TRIB1 and SPATA1) were hypomethylated regardless of tumor grade." (PMID 36850002, 2023).
SPATA1 also shares sentences with these, for which no sentence is quoted: glioma (1 paper); Globozoospermia (1).